TIA1 (TIA1 cytotoxic granule associated RNA binding protein)
Diseases named in the same sentence as TIA1 in open-access papers (continued):
Sharing a sentence is not in itself a finding about the gene and the disease.
Hepatic steatosis (3 papers, 2021 to 2025). Steatosis is a term used to denote lipid accumulation within hepatocytes. "In vivo silencing of TIA1 using AAV8-delivered shRNAs in mice worsens hepatic steatosis and fibrosis induced by a methionine and choline-deficient diet and increases the hepatic tumor burden in liver-specific PTEN knockout (LPTENKO) mice." (PMID 35406476, 2022). "Together, these data indicate that TIA1 deficiency in hepatocytes promotes the development in vivo of liver steatosis and fibrosis." (PMID 35406476, 2022). "Furthermore, TIA1 deficiency has been shown to promote hepatic steatosis and fibrosis in metabolic liver disease, which is associated with dysregulation of genes involved in lipid metabolism and inflammation." (PMID 41425091, 2025). "Core proteins involved in SGs assembly, including G3BP1, TIA1, DDX3X, and PDCD4, have been reported to be associated with fatty liver disease." (PMID 41425091, 2025). "Herein, we investigated in vivo the role for TIA1 in hepatic steatosis, inflammation, fibrosis and HCC development." (PMID 35406476, 2022). "Together, these results show that downregulation of TIA1 protein expression in hepatocytes fosters tumor initiation in a context of fatty liver disease." (PMID 35406476, 2022). "Finally, among the DEGs, some are also key regulators of hepatic lipid metabolism (e.g., PIK3R1, PPARG, S100A11), suggesting that alterations in TIA1 expression/activity also contribute to fatty liver disease development." (PMID 35406476, 2022). "Our bioinformatic analyses of publicly available databases or of mouse hepatic tissues did not allow for the observation of consistent alterations in TIA1 mRNA expression in human liver diseases, neither in mouse models of hepatic steatosis nor inflammation." (PMID 35406476, 2022).
lung carcinoma (3 papers, 2017 to 2025). "In cancer, TIA1 dysregulation has been reported in leukemia and lung cancer, yet its metabolic or immunological functions remain largely unexplored, and no study has connected TIA1 to BCG responsiveness in urothelial malignancy." (PMID 41300366, 2025).
lung squamous cell carcinoma (3 papers, 2015 to 2022). "TIA-1 is an RNA-binding protein that was found to be a relatively new tumor suppressor in patients with lung squamous cell carcinoma." (PMID 35776220, 2022). "Remarkably, low expressions of TIA1 and TIAR correlate with poor prognosis in patients with lung squamous cell carcinoma." (PMID 25741594, 2015).
motor neuron disease (3 papers, 2014 to 2022). "These seminal studies identified functional defects of SMN2 exon-7 splicing related to motor neuron disease and disassembly-assembly dynamics of SGs associated with the expression of the TIA1-WDM-mutated version." (PMID 35163320, 2022).
neuroblastoma (3 papers, 2010 to 2023). Neuroblastoma (NB) is the most common solid, extracranial childhood tumor. "Third, this study used a single ex vivo neuroblastoma population and a single stress stimulus for a specific length of time, which likely yielded only a subset of the potential proteome with which TIA1 interacts." (PMID 35205152, 2022). "Human BE-M17 neuroblastoma cells were exposed to arsenite (0.5 mM, 1 hr), the cells were fixed and then immuno-labeled with antibodies to TDP-43 or TIA-1." (PMID 20948999, 2010).
spinal muscular atrophy (3 papers, 2014 to 2018). A motor neuron disease that affect the muscles, and characterized by muscle weakness and atrophy resulting from progressive degeneration and irreversible loss of the anterior horn cells in the spinal cord (i.e., lower motor neurons) and the brain stem nuclei. "However, it has been recently shown that TIA1 is also a conditional gender-specific disease modifier in a mild mouse model of spinal muscular atrophy, because it enhances the impairment of male reproductive organ development and exacerbates the gene expression of the testis-specific transcriptome." (PMID 30533021, 2018).
steatosis (3 papers, 2021 to 2026). Increased lipid within the cytoplasm of cells. "Hepatocyte-specific TIA1 deletion exacerbated dietary-induced steatosis, inflammation, and fibrosis." (PMID 41876477, 2026). "Our in vivo data with mice fed an MCD diet, which induces severe steatosis and fibrosis further confirmed that TIA1 downregulation fosters lipid accumulation and fibrosis development in the liver." (PMID 35406476, 2022). "In agreement, using in vivo models, we found that contrary to our observations in HCC cells, TIA1 can exert a tumor suppressive function and refrain from hepatic steatosis and fibrosis." (PMID 35406476, 2022). "In this study, we found that TIA1 refrains from steatosis/fibrosis development and behaves as a potent hepatic TS, whose expression is lost in human HCC." (PMID 35406476, 2022). "Based on these in vitro data, we assessed in vivo the impact of TIA1 downregulation in the liver for the development of steatosis, inflammation and fibrosis in mice fed an MCD diet." (PMID 35406476, 2022). "Despite no changes in body parameters by TIA1 silencing in mice fed an MCD diet, we observed a strong induction of steatosis and fibrosis, but surprisingly not inflammation, in mice having an efficient knockdown of TIA1 in the liver." (PMID 35406476, 2022). "TIA1 nucleates SGs assembly and sequesters Srebf1 mRNA, leading to translational repression of the master lipogenic transcription factor SREBP1 and its downstream lipogenic program, thereby mitigating steatosis and subsequent inflammatory and fibrotic response." (PMID 41876477, 2026).
Anxiety (2 papers, 2022 to 2024). Intense feelings of nervousness, tension, or panic often arise in response to interpersonal stresses. "In summary, our study showed that solanesol can improve anxiety-like behaviors induced by CFA injections in mice by modulating TIA1 in the ACC." (PMID 39337650, 2024). "Based on the Western blotting and immunofluorescence results, solanesol produces a marked effect through TIA1 regulation, revealing the value of solanesol in treating anxiety, and indicating that TIA1 may be a potential new target for anxiety treatment." (PMID 39337650, 2024). "CFA was injected in the hind paws of TIA1Nestin conditional knockout (cKO) mice to confirm whether TIA1 is a potential modulatory molecule that influences pro-inflammatory cytokines and anxiety-like behaviors." (PMID 39337650, 2024). "Therefore, the mechanisms of TIA1 in the modulation of anxiety-like behaviors require further study." (PMID 39337650, 2024). "This suggests that TIA1 may be involved in SN’s regulation of anxiety." (PMID 39337650, 2024). "Indeed, only a few studies have been published on the role of TIA1 in anxiety-like behaviors." (PMID 39337650, 2024). "Subsequently, to confirm the role of TIA1 in human psychopathology, the authors conducted a population-based study that, although limited, identified a significant interaction between SNPs in TIA1 and stressful life events, which are related to the development of pathological anxiety symptoms." (PMID 35163320, 2022). "Our findings suggest that solanesol inhibits neuro-inflammation by decreasing the TIA1 level to reduce IL-1β and TNF-α expression, meanwhile inhibiting microglial and astrocytic activation in the ACC and ultimately ameliorating anxiety-like behaviors in mice." (PMID 39337650, 2024). "Here, we aimed to determine whether solanesol can reduce IL-1β and TNF-α levels by regulating TIA1 in the ACC, thereby improving anxiety-like behaviors in mice." (PMID 39337650, 2024). "However, whether the ratios of TIA1 and pro-inflammatory cytokines are directly or inversely proportional to each other in the ACC during the anti-anxiety process is unclear." (PMID 39337650, 2024). "However, the relationship between TIA1 in ACC and anxiety has not been clarified." (PMID 39337650, 2024).
Cognitive impairment (2 papers, 2018 to 2023). Abnormal cognition is characterized by deficits in thinking, reasoning, or remembering. "The cognitive impairment in family 1 may reflect the previously reported deleterious effects of the TIA1 and SQSTM1 variants on brain, as mutations in both genes have been identified in ALS and FTD." (PMID 29599744, 2018). "Thirteen percent of patients manifested cognitive impairment (VCP and SQSTM1 + TIA1)." (PMID 36861178, 2023).
experimental autoimmune encephalomyelitis (2 papers, 2025 to 2026). An autoimmune demyelinating disease of the central nervous system that is produced experimentally in animals by the injection of homogenized brain or spinal cord in Freund's adjuvant. "However, the role and mechanism of TIA1-mediated SGs in experimental autoimmune encephalomyelitis (EAE) remain unclear." (PMID 39804990, 2025). "In experimental autoimmune encephalomyelitis (EAE) mice, a model of MS, TIA1 and G3BP1+ (a cell marker of SGs) SGs were upregulated in retinal neurons and optic nerve astrocytes." (PMID 41758721, 2026).
hepatic cancer (2 papers, 2021 to 2022). "We also identified TIA1′s targets potentially implicated in its pathophysiological role and assessed its role in SG formation in hepatic cancer cells." (PMID 35406476, 2022). "Trans-well migration assays further indicated decreased migratory and invasive capacities of TIA1-deficient cells, thus supporting an oncogenic activity of TIA1 in transformed hepatic cancer cells as previously suggested." (PMID 35406476, 2022). "Herein, we further characterize TIA1’s functions in hepatic cancer cells by identifying an entire set of oncogenes and tumor suppressors under TIA1’s influence, thus suggesting a dual role in hepatocarcinogenesis." (PMID 35406476, 2022). "More recently, an oncogenic function of TIA1 was suggested in a hepatic cancer cell line (HepG2) based on its capacity to silence the TS gene IGFBP3." (PMID 35406476, 2022). "Consistent with a dual function of TIA1 in tumorigenesis, translatome analysis revealed that TIA1 appears to control the expression of both pro- and anti-tumorigenic factors in hepatic cancer cells." (PMID 35406476, 2022). "Consistent with this, resistance of hepatic cancer cells to sorafenib was reported to be associated with SG formation and TIA1 mRNA expression is increased in sorafenib non-responders." (PMID 35406476, 2022). "TIA1’s ability to promote SG assembly, which renders cancer cells more resistant to harmful conditions and anticancer treatments, has been reported in several non-liver cancers." (PMID 35406476, 2022). "Based on the reported tumor-suppressive role for TIA1 in non-liver cancers and our mouse data showing that TIA1 downregulation fosters tumor initiation, it is uncertain whether TIA1 protein is also upregulated in human HCC in line with its mRNA." (PMID 35406476, 2022). "Furthermore, we uncovered a role for TIA1 in cancer cell proliferation, migration and invasion in hepatic cancer cells." (PMID 35406476, 2022). "Such oncogenic activity remains to be confirmed in vivo as well as whether TIA1 is required for SG formation in hepatic cancer cells." (PMID 34502337, 2021). "Finally, TIA1′s interaction with lncRNAs, e.g., MALAT1 and NEAT1, which display oncogenic features in HCC, likely also contributes to the tumor-suppressive effect of TIA1, since we could show that TIA1 silencing promotes NEAT1 upregulation in hepatic cancer cells." (PMID 35406476, 2022). "TIA1 mRNA expression is indeed upregulated in HCC and hepatic cancer cells and can act as an oncogene due to its ability to silence the tumor suppressor IGFBP3." (PMID 34502337, 2021). "Currently, very few therapeutic options are available for HCC but also other hepatic cancers (i.e., ICC, hepatoblastoma), and thus a better understanding of TIA1 but also of other AUBPs may provide new biomarkers and/or novel and efficient therapeutic options." (PMID 35406476, 2022). "Here we provide evidence that although TIA1 is required for fully efficient SG assembly induced by sorafenib, its downregulation cannot entirely prevent it, nor fully restore sorafenib sensitivity in hepatic cancer cells." (PMID 35406476, 2022). "Finally, our study indicates that TIA1 colocalizes with SGs, but is not strictly required for their formation in hepatic cancer cells." (PMID 35406476, 2022). "However, although TIA1 silencing in these cells may impair SG formation (absence of G3BP1 positive SG when TIA1 is silenced in some cells), it only slightly impairs sorafenib resistance of hepatic cancer cells." (PMID 35406476, 2022).
hepatocellular carcinoma (2 papers, 2016 to 2022). A malignant tumor that arises from hepatocytes. "The overexpression of TIA1 transcript has been reported in hepatocellular carcinoma tissues compared with paired adjacent non-tumor tissues using multiple samples." (PMID 26958940, 2016).
ischemic stroke (2 papers, 2020 to 2026). A stroke disorder caused by obstruction of blood flow to the brain, due to thrombotic (local blood clot formation) or embolic (due to a blood clot or other material traveling from another site) event. "Knockout of TIA1 in neural tissue has been shown to increase expression of CCNF and CDKN1, cell cyclin proteins that are expressed during microglial proliferation after ischemic stroke." (PMID 32327969, 2020).
lymph node metastases (2 papers, 2014 to 2015). "We could not demonstrate a significant association for other markers of the adaptive immune system, although activated T-cells expressing the TIA-1 marker correlated with lack of lymph node metastases in a univariate analysis." (PMID 25609852, 2014).
non-Hodgkin lymphoma (2 papers, 2020 to 2021). Distinct from Hodgkin lymphoma both morphologically and biologically, non-Hodgkin lymphoma (NHL) is characterized by the absence of Reed-Sternberg cells, can occur at any age, and usually presents as a localized or generalized lymphadenopathy associated with fever and weight loss. "Natural killer/T-cell lymphoma (NKTCL) is a highly invasive subtype of non-Hodgkin lymphoma, typically positive for cytoplasmic CD3, CD56, cytotoxic markers, including granzyme B and TIA1, and Epstein-Barr virus (EBV)." (PMID 33628584, 2021).
osteosarcoma (2 papers, 2017 to 2018). A usually aggressive malignant bone-forming mesenchymal neoplasm, predominantly affecting adolescents and young adults. "Our findings support the hypothesis that CD8/Tia1 infiltrate in tumor microenvironment at diagnosis confers superior survival for pts with localized osteosarcoma, while PD-L1 expression is associated with worse survival." (PMID 29340095, 2017). "SIN-1 induces the formation of SGs in U2OS osteosarcoma cells as analyzed by colocalization of G3BP1 and TIA-1, two canonical SG markers." (PMID 30425239, 2018). "The present study, including patients with osteosarcoma in a localized stage, and treated within the same protocol, demonstrated an independent prognostic role of CD8+ and Tia1 lymphocytes." (PMID 29340095, 2017). "Tia1+ lymphocytes might represent a more efficient subset of CD8+ effector cells, playing an important role in immune-surveillance of osteosarcoma." (PMID 29340095, 2017).
panniculitis (2 papers, 2021 to 2025). Inflammation of the subcutaneous adipose tissue. "Due to its nonspecific presentation and histological overlap with panniculitis, early diagnosis requires a high index of suspicion, prompt biopsy of nodular lesions, and immunophenotyping using markers such as CD2, CD3, CD8, granzyme B, and TIA-1." (PMID 40709991, 2025).
squamous cell carcinoma (2 papers, 2015 to 2016). A carcinoma arising from squamous epithelial cells. "A similar pattern of TIA1 immunoreactivity was observed in squamous cell carcinomas of other tissues." (PMID 26958940, 2016). "Because TIA1 overexpression and cytoplasmic localization are commonly observed in various squamous cell carcinomas, cancer-promoting effects of TIA1 through cytoplasmic localization might be cell lineage-specific." (PMID 26958940, 2016).
Stroke (2 papers, 2023 to 2026). Sudden impairment of blood flow to a part of the brain due to occlusion or rupture of an artery to the brain. "This review discusses the molecular structure and functions of TIA1, focusing on its expression in neurons and glia, as well as its implications in neurodegenerative disorders and stroke." (PMID 41828481, 2026). "RIC significantly increased G3BP1, TIA1, and DDX3X levels in mRNA and protein expressions at Day 3 after stroke." (PMID 37580991, 2023).
thyroid cancer (2 papers, 2022). "LINC00894 was downregulated in thyroid cancer tissues and inhibited the cancer cell proliferation, migration, and invasion by acting as a sponge of let-7e-5p to regulate TIA-1 protein levels." (PMID 35776220, 2022). "In conclusion, our data suggest that increased LINC00894 expression reduces the oncogenic properties of thyroid cancer cells by sponging let-7e-5p to promote TIA-1 expression." (PMID 35776220, 2022). "TIA-1 was significantly downregulated in thyroid cancer include follicular thyroid cancer and papillary thyroid cancer and this low TIA1expression was related to poor prognosis according to GEPIA2 and Kaplan–Meier survival analyses." (PMID 35776220, 2022). "Second, we did not perform in vivo experiments to verify the effect of the LINC00894/let-7e-5p/TIA-1 pathway on the growth and metastasis of thyroid cancer." (PMID 35776220, 2022). "Finally, LINC00894 inhibited thyroid cancer cell proliferation, migration, invasion by acting as a sponge of let-7e-5p to promote TIA-1 expression." (PMID 35776220, 2022). "Meanwhile, TIA-1 expression in thyroid cancer cells was analyzed via western blotting." (PMID 35776220, 2022). "Finally, let-7e-5p weakened the function of LINC00894 in thyroid cancer cells via reduction in TIA-1 levels." (PMID 35776220, 2022). "TIA-1 expression had no significantly changed between follicular thyroid cancer, papillary thyroid cancer, and other thyroid cancer." (PMID 35776220, 2022).
anaplastic large cell lymphoma (1 paper, 2013). Anaplastic large cell lymphoma (ALCL) is a rare and aggressive peripheral T-cell non-Hodgkin lymphoma, belonging to the group of CD30-positive lymphoproliferative disorders, which affects lymph nodes and extranodal sites. "In childhood, ALK-positive anaplastic large cell lymphoma is a major type of CD4- and TIA1-positive cytotoxic T/NK-cell lymphoma." (PMID 23302373, 2013). "The present case is a CD3-, CD4- and TIA1-positive and CD30-negative (Th1) large-cell lymphoma without EBV infection." (PMID 23302373, 2013).
ankylosing spondylitis (1 paper, 2015). An autoimmune chronic inflammatory disorder characterized by inflammation in the vertebral joints of the spine and sacroiliac joints. "For rheumatoid arthritis, systemic lupus erythematosus, ankylosing spondylitis and osteoarthritis diseases, those common factors include TNFSF10, CX3CR1, LY96, TLR5, TXN, TIA1, PRKCH, and PRF1." (PMID 26352601, 2015).
anxiety disorder (1 paper, 2024). A category of psychiatric disorders which are characterized by anxious feelings or fear often accompanied by physical symptoms associated with anxiety. "Drugs targeting TIA1 may offer new avenues for anxiety disorder treatment." (PMID 39337650, 2024).
astrocytoma (1 paper, 2013). "We may suggest that the tumor suppressive potential of miR-106a-5p is due to inhibition of FASTK which interacts with TIA1 to mediate Fas-induced apoptosis during astrocytoma pathogenesis." (PMID 24013584, 2013).
atrial fibrillation (1 paper, 2018). A disorder characterized by an electrocardiographic finding of a supraventricular arrhythmia characterized by the replacement of consistent P waves by rapid oscillations or fibrillatory waves that vary in size, shape and timing and are accompanied by an irregular ventricular response. "The myopathic respiratory insufficiency and atrial fibrillation (although the latter finding could an incidental finding) in family 2’s proband emphasize the need to investigate respiratory and cardiac function in future cases of SQSTM1/TIA1 myopathy." (PMID 29599744, 2018).